ENSG00000238906
Synonyms: LOC124901827
Gene: Small nucleolar RNA gene on chromosome 7 (29,912,528 to 29,912,632, forward strand). Ensembl gene ENSG00000238906.
Gene Ontology:
Biological process: RNA processing
Cellular component: nucleolus
Homologues: Paralogues in human: SNORD13 (89% identical), SNORD13P3 (88% identical), SNORD13P1 (85% identical), SNORD13D (83% identical), SNORD13E (83% identical).